ZBTB49 (zinc finger and BTB domain containing 49)
Description:
Transcription factor. Inhibits cell proliferation by activating either CDKN1A/p21 transcription or RB1 transcription. [Isoform 1]: Binds CDKN1A promoter and activates its transcription; this activity is further potentiated in the presence of EP300 (synergistic) and ZBTB17/Miz-1 (additive). [Isoform 3]: Activates RB1 transcription most probably by antagonizing ZBTB17 repression of RB1. Does not bind directly RB1 promoter.
Synonyms: ZNF509; FLJ38559
Tractability: No criterion of Open Targets' tractability assessment is met for any kind of drug.
Gene: Protein-coding gene on chromosome 4 (4,290,238 to 4,321,786, forward strand). Ensembl gene ENSG00000168826.
Subcellular location: Cytoplasm (Isoform 1); Nucleus; Cytoplasm (Isoform 3)
Subcellular location (Human Protein Atlas): Nucleoplasm; Cytosol; Microtubules
Gene Ontology:
Molecular function: DNA-binding transcription factor binding; protein binding; sequence-specific DNA binding; transcription coactivator binding; DNA-binding transcription repressor activity, RNA polymerase II-specific; RNA polymerase II cis-regulatory region sequence-specific DNA binding; DNA binding
Biological process: negative regulation of cell population proliferation; positive regulation of transcription by RNA polymerase II; regulation of cell cycle; negative regulation of transcription by RNA polymerase II; regulation of cytokine production; regulation of immune system process; positive regulation of DNA-templated transcription; regulation of transcription by RNA polymerase II
Cellular component: cytoplasm; nucleus; nucleoplasm
Genetic constraint (gnomAD): Loss-of-function variants: 25 observed, 42.22 expected, observed/expected ratio (o/e) 0.59, 90% interval 0.43 to 0.83. The upper end of that interval is the gene's LOEUF score, 0.83, which puts it in group 3 of 6, group 1 being the genes least tolerant of losing a copy. Missense variants: 685 observed, 740.37 expected, observed/expected ratio (o/e) 0.93, 90% interval 0.87 to 0.99. Synonymous variants: 265 observed, 284.9 expected, observed/expected ratio (o/e) 0.93, 90% interval 0.84 to 1.03.
Homologues: Orthologues: chimpanzee ZBTB49 (99% identical), macaque ZBTB49 (97% identical), dog ZBTB49 (82% identical), pig ZBTB49 (77% identical), rabbit ZBTB49 (76% identical), guinea pig ZBTB49 (74% identical), mouse Zbtb49 (74% identical), rat Zbtb49 (73% identical), tropical clawed frog zbtb49 (55% identical), zebrafish zbtb49 (38% identical). Paralogues in human: FEZF1 (17% identical), BCL6 (16% identical), FEZF2 (16% identical), ZBTB7B (15% identical), BCL6B (14% identical), ZBTB21 (14% identical), ZBTB46 (14% identical), ZBTB14 (13% identical), ZNF280D (13% identical), ZNF683 (13% identical), PRDM13 (12% identical), ZBTB33 (11% identical), and 16 more.
Diseases named in the same sentence as ZBTB49 in open-access papers:
ZBTB49 is named in the same sentence as 2 diseases in open-access papers, as found by Europe PMC text mining. Sharing a sentence is not in itself a finding about the gene and the disease. The quoted sentences say what the papers report.
skin tumor (1 paper, 2024). "ZBTB49 is highly expressed in normal epithelial cells, as was shown by the immunohistological analysis but is repressed in colon, lung, and skin tumor tissues." (PMID 39596218, 2024).
ZBTB49 also shares sentences with these, for which no sentence is quoted: tumor (1 paper).